INS (insulin)
Diseases named in the same sentence as INS in open-access papers (continued):
Sharing a sentence is not in itself a finding about the gene and the disease.
Insulin resistance (continued). "Of those assessed at high risk or with potentially undiagnosed T2DM and plasma insulin levels measured to allow HOMA‐IR calculation (n = 113), 81 (71.7%) had HOMA levels > 1.7 molar units which also demonstrates high levels of insulin resistance in this cohort." (PMID 25581207, 2015). "In addition, BC ameliorated insulin resistance by decreasing insulin release, improving glucose tolerance, and restoring insulin signaling by recovering IRS-1 expression in skeletal muscle tissue." (PMID 26504474, 2015). "In support of S1P activation in diabetic control, S1P has been shown to be important for insulin synthesis and secretion in a rat insulinoma cell line, muscle insulin resistance, and adiponectin action (increased sensitivity, decreased inflammation, and prosurvival)." (PMID 25866760, 2015). "Firstly, BBR improved insulin sensitivity in T2DM characterized by insulin resistance." (PMID 25861268, 2015). "Elevated sympathetic activity could antagonise insulin’s effect on glucose uptake via effects on blood flow(sympathetically mediated vasoconstriction) in skeletal muscle, result in hyperinsulinemia and insulin resistance." (PMID 26423242, 2015). "There are also examples of steatosis without being associated with hepatic insulin resistance; steatosis occurs even when insulin sensitivity is dramatically improved." (PMID 25909991, 2015). "Insulin stimulates chemerin secretion, promoting a vicious circle increasing insulin resistance." (PMID 26124830, 2015). "It has been suggested that leptin may contribute to hepatic steatosis by promoting insulin resistance and by altering insulin signaling in hepatocytes, so as to promote increased intracellular fatty acids." (PMID 26569494, 2015). "For example, following insulin resistance and hyperinsulinaemia which are common features of type 2 diabetes, the transport of insulin into the brain across the blood brain barrier is reduced and this lowers the insulin levels in the brain." (PMID 26193295, 2015). "Few studies have investigated insulin sensitivity in matched severely obese men and women, who are exceptionally prone to develop insulin resistance, or described gender differences in tissue-specific measurements of insulin sensitivity in liver and adipose tissue of men and women." (PMID 26635731, 2015). "As a result, we cannot exclude that deterioration of insulin resistance induced by the hepatic inflammation may have been overcome by the insulin sensitizing effect of cholesterol." (PMID 25815343, 2015). "Improvement in risk factors associated with the metabolic syndrome, namely insulin resistance, hyperglycemia, proinflammatory state, blood pressure and HDL-cholesterol may underlie the vascular benefit and enhancement in insulin clearance." (PMID 26297500, 2015). "Despite this increase in insulin resistance, however, there was no detectible association between the degree of changes in insulin sensitivity and the severity of atherosclerosis in the pigs in this study." (PMID 26147990, 2015). "Our results showed that fasting blood glucose, serum insulin level, insulin resistance index and C-peptide level in the high dose group had a significant downward trend when compared with the model group, chromium picolinate group and chromium trichloride group." (PMID 25942313, 2015). "Insulin resistance may arise from downregulation of key components of the insulin signaling pathway." (PMID 26302954, 2015). "While insulin resistance is thought to be a primary factor in the pathogenesis of T2D in Caucasian, Mexican–American, and Pima Indian populations, impaired insulin secretion has been reported to be a major factor in T2D in Japanese." (PMID 26366137, 2015). "Glucose uptake and consumption were improved in the rapamycin plus TNF-α or IL-6 groups compared with cells treated with TNF-α or IL-6 alone in the absence and presence of insulin, suggesting that rapamycin ameliorates inflammatory stress-induced insulin resistance in vitro." (PMID 26449763, 2015).
Insulin resistance (continued). "Also, for the evaluation of insulin sensitizing drugs, the presence of insulin resistance is needed." (PMID 25785279, 2015). "Therefore, future studies employing more sensitive measures of insulin resistance, such as insulin or glucose clamp studies will be necessary to accurately determine the precise degree of insulin resistance in the male CD24KO mice on each diet." (PMID 26536476, 2015). "Novel Akt2 interactions may further elucidate insulin signaling and provide insight into abnormal Akt2 protein interaction that contributes to the development of insulin resistance and/or type II diabetes." (PMID 26465754, 2015). "Mercury exposure causes a modest increase in glucose transport and may contribute to the development of insulin resistance by elevating glucose levels compared to insulin." (PMID 33889422, 2015). "On the other hand, fasting insulin and glucose are part of another module which displays an immune signature (Adhesion and Diapedesis), emphasizing the link between adipose tissue inflammatory status and insulin resistance." (PMID 25590576, 2015). "High dose of insulin also improved peripheral insulin resistance in APOE positive patients." (PMID 26136647, 2015). "It is however unexpected that the T2D risk allele associates with increased insulin secretion, when it does not seem to associate with increased insulin resistance either in our or MAGIC consortium data." (PMID 25799151, 2015). "A few studies have investigated the association between glucose, insulin, insulin resistance, and memory function in non-diabetic middle-aged individuals." (PMID 25798199, 2015). "The accumulation of β-amyloid did not exacerbate the first phase of glucose tolerance possibly due to a slight increase in insulin secretion, but serum glucose levels during the second phase reached a higher peak and decreased slowly, indicating severe glucose intolerance and insulin resistance." (PMID 25755673, 2015). "Changes in insulin sensitivity (IS) and insulin secretion occur with perturbations in energy balance and glycemic load (GL) of the diet that may precede the development of insulin resistance and hyperinsulinemia." (PMID 25723719, 2015). "However, GB extract feeding in C57BL/6 mice for 6 months starting at 15 months of age resulted in a significant decrease of HOMA-IR, which is a well-defined biomarker for the assessment of insulin resistance and insulin sensitivity." (PMID 25912041, 2015). "For example, aberrant subcellular signaling of zinc concentrations in the cytosol and organelles may contribute to insulin responsiveness and thus promote insulin resistance." (PMID 25983752, 2015). "Insulin resistance increases the insulin demand of the organism." (PMID 26108563, 2015). "Fourth, the fetal insulin hypothesis suggests that both low birth weight and insulin resistance may be mediated by the same inheritable genes because insulin plays an important role in fetal development." (PMID 26561832, 2015). "Also, insulin levels increased substantially from this point on, indicating the development of insulin resistance." (PMID 25962520, 2015). "As islet architecture was destroyed with age in ZFDM rats, a combination of severe insulin resistance, diminished insulin secretory response to incretin, and intrinsic fragility of the islets may cause the development of T2D in this strain." (PMID 25961052, 2015). "In addition, many interventions that improve insulin resistance can also affect the secretion of insulin." (PMID 26106625, 2015). "Inflammatory cytokines may also impair insulin action in peripheral tissues and increase insulin resistance, dyslipidemia, and hypertension in OSA." (PMID 26391008, 2015). "Additionally, mice with higher levels of Aβ1-40 and Aβ1-42 in plasma showed hyperinsulinemia, impaired insulin signaling in the liver, glucose intolerance, and insulin resistance." (PMID 26340637, 2015).
Insulin resistance (continued). "In addition, exercise has been reported to have a beneficial effect on tumor outcomes by reducing insulin resistance and insulin and IGF-1 secretion." (PMID 26458923, 2015). "Inhibitors of this pathway are used for cancer therapy but such drugs may result in impaired insulin responses and insulin resistance leading to the development of type 2 diabetes." (PMID 25866760, 2015). "In addition, we previously reported that the overexpression of iNOS contributes to hepatic insulin resistance via the S-nitrosylation of insulin signaling molecules." (PMID 26172834, 2015). "These evidences have revealed that insufficient sleep and sleep fragmentation alter physiological mechanisms such as diminished brain glucose utilization; increased sympathetic nervous system activity; and inhibited insulin secretion and promoted insulin resistance." (PMID 26351585, 2015). "The MUFA-rich diet improved insulin sensitivity, and lowered insulinresistance (homoeostasis model assessment-insulin resistance) to a greater extent comparedwith the high-SFA and the high-carbohydrate diets (2·32 (sd 0·3), 2·74 (sd0·4), 2·52 (sd 0·4), respectively, P<0·01)." (PMID 26411958, 2015). "However, chronic treatment (24 h) with this cytokine has been demonstrated to be able to cause insulin resistance in C2C12 murine myotube cell line, due to impairment of insulin signaling (IRS/AKT cascades) in a JNK1/2-dependent manner." (PMID 25814786, 2015). "Iron is a potent metal, which could potentially interfere with insulin synthesis and secretion in the pancreas, leading to insulin resistance or reduced insulin secretion." (PMID 26347777, 2015). "In this article, we revisit the pathogenesis of T2DM with reference to β cell dysfunction versus insulin resistance, together with incretin secretion and action, in East Asians and discuss ethnic differences in the contributions of insulin secretion and insulin resistance to glucose intolerance." (PMID 25944304, 2015). "Pro-inflammatory cytokines produced by both adipocytes and infiltrating immune cells directly interfere with the insulin signalling pathway, thereby affecting insulin sensitivity both locally and systemically, leading to insulin resistance (IR) and type 2 diabetes." (PMID 25962520, 2015). "Third, exclusion of diabetic patients under treatment with insulin or sulphonylureas may have introduced selection bias given the likelihood of systematic exclusion of subjects with the most severe insulin resistance." (PMID 26542243, 2015). "Hyperglycemia results when insulin secretion is unable to compensate for insulin resistance." (PMID 25982967, 2015). "Third, clinically it is not easy to obtain optimal physiological level of insulin to sustain glycemic control by exogenous insulin administration and therefore hyperinsulinemia is unavoidable in the presence of insulin resistance, leading to a vicious cycle favoring the development of breast cancer." (PMID 26537234, 2015). "Thus, the mitogenic effects of exogenous insulin can be exaggerated when insulin resistance and some precancerous or early cancerous lesions are present." (PMID 26171401, 2015). "Nevertheless, dyslipidemia may also occur as a result of insulin resistance since hepatic lipogenesis, in contrast to gluconeogenesis, remains sensitive to insulin." (PMID 25815343, 2015). "Insulin resistance that is characterized by reduced sensitivity and response to insulin action of insulin-sensitive organs is an important pathogenic factor for type 2 diabetes triggered by excess nutrient intake, in addition to impaired insulin secretion caused by pancreatic β cell dysfunction." (PMID 25887856, 2015). "Due to the key inter-related roles of hypertension, chronic inflammation and insulin resistance in the pathogenesis of metabolic syndrome, there is growing interest in investigating established anti-hypertensive agents for their effects on insulin sensitivity and inflammation." (PMID 25714093, 2015).
Insulin resistance (continued). "In addition, more recent studies indicated that, compared to individuals without BAT, the BAT-positive subjects were younger, had lower body mass index, fasting insulin, insulin resistance, but a greater level of high-density lipoprotein cholesterol." (PMID 25688211, 2015). "Hyperinsulinemia is widely considered a consequence of insulin resistance where β-cells, as a compensatory response to the insulin-resistant state, produce and secrete increased levels of insulin, resulting in elevated basal levels of insulin but normoglycemia." (PMID 26085100, 2015). "In conclusion, contrary to our hypothesis, we found that low-aerobic capacity was associated with enhanced aortic endothelial function and NO-mediated reactivity to insulin, despite increased adiposity and evidence of whole body insulin resistance." (PMID 26197933, 2015). "Insulin resistance is characterized by decreased insulin action on peripheral organs (primarily the liver and the skeletal muscle) and reduced phosphorylation and activation of the insulin receptor (IR), IRSs and components of the phosphatidylinositol 3-kinase/protein kinase B (AKT) pathway." (PMID 25822220, 2015). "Given visfatin's insulin-mimetic actions, some authors have suggested visfatin may be elevated to compensate for insulin resistance and to prevent further resistance to insulin." (PMID 26124830, 2015). "We demonstrated that OVX-induced estrogen deficiency exacerbated hyperglycemia and glucose intolerance, increased plasma insulin levels, and induced insulin intolerance and insulin resistance in female mice exposed to inorganic arsenic in drinking water at doses relevant to human exposure." (PMID 25859628, 2015). "However, glucocorticoid receptor number had a strong correlation with insulin, due to insulin resistance, but this characteristic was lost after treatment." (PMID 26269722, 2015). "Others’ and our previous studies have reported that vascular insulin resistance, which is characterized by blunted insulin-induced vasorelaxation or imbalance of vascular insulin signaling, occurs before systemic insulin resistance in hypertensive and high-fat diet models." (PMID 25793876, 2015). "Secondly, it is possible that insulin resistance in these subjects/mice is mainly due to muscle or liver insulin resistance and that adipose tissue may respond to insulin in a relatively normal fashion." (PMID 26150553, 2015). "Selective insulin resistance refers to the observation that although insulin-mediated suppression of gluconeogenic pathways is impaired in insulin-resistant liver, another pathway that stimulates de novo lipogenesis through the sterol response element binding protein (SREBP1) remains intact." (PMID 26273583, 2015). "In contrast, a 24-week study in nine patients with stable active plaque psoriasis treated with etanercept found a significant reduction in insulin plasma levels, with a significant improvement in insulin resistance as suggested by the decrease in the HOMA index." (PMID 25654080, 2015). "Furthermore, women with typical PCOs had acanthosis nigricans, raising the possibility of being insulin resistant, similar to women with the rare syndromes of extreme insulin resistance." (PMID 25866568, 2015). "To evaluate whether insulin resistance was induced in response to P. panacis EVs, we performed insulin-tolerance test (ITT) and glucose-tolerance test (GTT)." (PMID 26510393, 2015). "The impaired GLUT4 translocation to sarcolemma under insulin stimulation may mediate insulin resistance in unloaded soleus muscle and further affect the insulin sensitivity of whole body in tail-suspended rats." (PMID 25713812, 2015). "Evidence suggests that brain insulin resistance co-occurs with peripheral insulin resistance, with insulin-resistant individuals demonstrating reduced glucose metabolism in the VS and prefrontal cortex in response to peripheral insulin." (PMID 25716779, 2015).
Insulin resistance (continued). "Elevated plasma TNF-α levels may be an important mediator of insulin resistance by impairing insulin signaling." (PMID 26666849, 2015). "Understanding the mechanism by which TUSC5 interacts and regulates with insulin-regulated GLUT4 traffic may provide novel insight into this system and the defects associated with insulin resistance." (PMID 26240143, 2015). "However, the breadth of responses to TUSC5 knockdown and because TUSC5 is required for PPARγ-mediated reversal of insulin resistance suggest a longer term role in modulating insulin responses in adipocytes." (PMID 26240143, 2015). "Insulin resistance is defined as a reduced response to insulin in liver, muscle, and AT." (PMID 26779183, 2015). "While it has become apparent that there is not a direct causal relationship linking fatty liver to insulin resistance, reductions in hepatic triglyceride levels generally coincide with improved insulin sensitivity." (PMID 25849936, 2015). "IGF-1 has structural and functional homology with insulin, and it has been suggested that insulin resistance might lead to increased IGF-1 bioavailability to compensate for reduced insulin action." (PMID 26568155, 2015). "Based on the previous studies, it could be observed that a high salt diet could induce insulin resistance and could produce insulin secretion." (PMID 26216433, 2015). "In conclusion, the present study demonstrated that CGE has antidiabetic and renoprotective effects in T2DM by restoration of pathogenic consequences, including antihyperglycaemia, antihypertriglyceridemia, anti-insulin resistance, and restoration of insulin stimulated renal rOat1 and 3 functions." (PMID 25883984, 2015). "Because FGF21 and insulin action are likely interacting, we proposed that, similarly to insulin resistance, ectopic lipid accumulation could impair FGF21 signaling." (PMID 25973847, 2015). "Several pathophysiological mechanisms contribute to the evolution of T2DM, including increased insulin resistance in the skeletal muscle and liver; augmented hepatic glucose output; impaired insulin secretion with progressive decline of pancreatic β cell function." (PMID 26075286, 2015). "In addition, plasma insulin in the insulin resistance rat model correlates positively with plasma Hcy." (PMID 26561832, 2015). "With insulin stimulation, activated pAKT is used as an indication of insulin resistance." (PMID 26193363, 2015). "In addition, insulin resistance and impaired insulin secretion are strongly influenced by uric acid levels." (PMID 25617895, 2015). "Counterbalance between insulin secretion and insulin resistance is critical for T2DM pathogenesis." (PMID 25944304, 2015). "However, insulin resistance is often undiagnosed due to the possibility of an insulin-resistant patient to have normal blood glucose." (PMID 26217525, 2015). "To explore which organ may be responsible for insulin resistance, we analyzed insulin-induced phosphorylation of the insulin receptor (p-IRβ)." (PMID 25757720, 2015). "The fasting insulin level exceeding 15 μIU/ml and indicating hyperinsulinemia was observed in 19 (48.71 %) patients with severe obesity and additionally 67 % of patients with severe obesity were diagnosed with insulin resistance." (PMID 26379783, 2015). "Thus, in the case of obesity and insulin resistance, the levels of insulin penetrating the brain can be increased, provided high levels of circulating triglycerides." (PMID 26041981, 2015). "Regular low-to-moderate alcohol consumption has been shown to improve insulin sensitivity, but chronic heavy alcohol intake may promote insulin resistance." (PMID 27525252, 2015). "Reducing the level of serum AST, ALP, insulin, decrease BMI and insulin resistance index." (PMID 26633388, 2015). "In a study of 72 human subjects who underwent insulin clamp studies, skeletal muscle and adipose tissue biopsies, impaired fatty acid and branched chain amino acid metabolism were proportional to the degree of insulin resistance." (PMID 25784953, 2015).